RNU6-474P (RNA, U6 small nuclear 474, pseudogene)
Gene: Small nuclear RNA gene on chromosome 2 (203,782,037 to 203,782,143, forward strand). Ensembl gene ENSG00000206970.
Homologues: Orthologues: chimpanzee U6 (98% identical), macaque U6 (93% identical), pig U6 (76% identical), rabbit U6 (75% identical), mouse Gm23958 (74% identical), pig U6 (74% identical). Paralogues in human: RNU6-1060P (93% identical), RNU6-116P (91% identical), RNU6-15P (91% identical), RNU6-19P (91% identical), RNU6-26P (91% identical), RNU6-1024P (90% identical), RNU6-12P (90% identical), RNU6-13P (90% identical), RNU6-266P (90% identical), RNU6-31P (90% identical), RNU6-32P (90% identical), RNU6-33P (90% identical), and 1290 more.